LPL (lipoprotein lipase)
Diseases named in the same sentence as LPL in open-access papers (continued):
Sharing a sentence is not in itself a finding about the gene and the disease.
hyperlipidemia (continued). "In ponies with hyperlipidemia, the activity of lipoprotein lipase, which is responsible for peripheral catabolism of TG, is doubled than that in healthy ponies, likely as a physiological response to the increased concentration of substrate." (PMID 34947937, 2021). "Chondroitin sulfate A from Emerald mussel enhances the activity of lipoprotein lipase (LPL), leading to a reduction in TC and TG serum levels in patients with hyperlipidemia." (PMID 34532028, 2021). "Even though the mechanisms that cause hyperlipidemia in lupus patients is not well understood, some studies have suggested that the activity of enzyme lipoprotein lipase (LPL), which metabolizes lipids, is reduced and autoantibodies to LPL could be a reason for its reduced activity." (PMID 30061888, 2018). "This is consistent with the work of others reporting that bacterial endotoxin causes ‘lipemia of sepsis’ by increasing VLDL-mediated triglyceride release from hepatocytes, and by limiting lipoprotein lipase-mediated VLDL clearance in peripheral tissues." (PMID 30563203, 2018). "Red ginseng saponins (0.01 g/kg for 4 weeks) sustained LPL activity at a normal level or protected LPL activity, resulting in reduction of the rise in serum TG and TC in a cyclophosphamide-induced hyperlipidemia fasted rabbit model." (PMID 25110708, 2014). "LPL plays an important role in hyperlipidemia, and hyperlipidemia is a common complication of preeclampsia." (PMID 24312300, 2013). "This smaller aberrant particle reaches the circulation where it cannot be efficiently hydrolyzed by LpL, resulting in hyperlipidemia." (PMID 23145182, 2012). "This compound inhibits lipoprotein lipase resulting in increased cholesterol and triglycerides levels in plasma and thus it has been widely used for induction of acute hyperlipidemia and for assay of putative hypocholesterolemic drugs." (PMID 22073134, 2011). "A PPARγ ligand, pioglitazone, suppressesboth hyperlipidemia and intestinal polyp formation in the APC-deficient mice inconjunction with elevation of lipoprotein lipase (LPL), which catalyzes TGhydrolysis." (PMID 18483618, 2008). "Patients who did not have APOE2/2 genotype were grouped according to the form of hyperlipidemia and the frequencies of the LPL SNPs compared." (PMID 17727701, 2007). "Mechanistically, OSA-induced hyperlipidemia may arise from impaired lipoprotein clearance due to suppressed lipoprotein lipase (LpL) activity." (PMID 40612801, 2025). "Also, the author reviews molecular pathways including the ApoA-1, ApoE, and LPL genes, which are related to hyperlipidemia, to explain the results." (PMID 39598239, 2024). "Moreover, in recently published data from our lab, severe diabetes with concomitant hyperglycemia and hyperlipidemia reduced Hpa secretion from the isolated heart, a possible explanation for the lowered coronary LPL activity in these hearts." (PMID 39081272, 2024). "Similarly, flavonoids obtained from PL significantly decreased TC, TAG, and LDL-C, but increased HDL-C, lipoprotein lipase (LPL), and hepatic lipase (HL) in the lipid metabolic disorder of hyperlipidemia rats, indicating its lipid-lowering effect." (PMID 36840285, 2023). "Similarly, it was reported that the curcumin‐free MG extract was capable of reversing hyperlipidemia by elevating lipoprotein lipase activity in triton WR‐1339 induced‐hyperlipidemic rats." (PMID 37823118, 2023). "This imbalance could induce hyperlipidemia from the adipose tissue's lipid mobilization or due to the decreased lipoprotein lipase activity that reduced the uptake of lipids by the adipose cells." (PMID 36942197, 2023). "In addition, fructose can cause a decrease in lipoprotein lipase, which in turn reduces VLDL level and the clearance of TG-rich lipoproteins, eventually leads to elevated serum TG and NAFA, inducing severe hyperlipidemia." (PMID 35928832, 2022).
hyperlipidemia (continued). "The hyperlipidemia effects of dexamethasone observed in the present study may be attributed to lowering lipoprotein lipase activity and increasing hepatic and intestinal production of very low-density lipoprotein cholesterol (VLDL)." (PMID 35326092, 2022). "Moreover, studies have shown that high doses of phenolic compounds can prevent hyperlipidemia by increasing LPL activity." (PMID 34401109, 2021). "The protective effects against hyperlipidemia might be attributed to the improvement of serum LPL mediated TG hydrolysis and inhibition of hepatic HMGR mediated cholesterol synthesis pathway." (PMID 35557892, 2018). "This randomized, double-blind, placebo-controlled trial revealed that mangiferin supplementation for 12 weeks significantly decreased the serum TG, FFA, and HOMA-IR levels and increased the serum mangiferin, HDL, and LPL levels in overweight patients with hyperlipidemia." (PMID 25989216, 2015). "Two patients with other five family members were included in this study for DNA-sequences of hyperlipidemia-related genes (such as LPL, APOC2, APOA5, LMF1, and GPIHBP1) and 43 healthy individuals and 70 HTG subjects were included for the screening of LPL gene mutations." (PMID 24646025, 2014). "Plasma lipid concentrations in the combined hyperlipidemia subjects, grouped by LPL genotype." (PMID 16822320, 2006). "Notably, in vivo studies have shown that polyphenol-rich apple extract may reduce TG levels by increasing LPL activity in a model of Triton WR-1339-induced endogenous hyperlipidemia." (PMID 41515154, 2025). "Inhibition of LPL expression may the mechanism by which ANGPTL3 induces hyperlipidemia in PNS." (PMID 35399079, 2022). "Finally, we explored the role of LPL in the mechanism of ANGPTL3 in PNS hyperlipidemia." (PMID 35399079, 2022). "Inhibiting LPL expression may be the mechanism by which ANGPTL3 induces hyperlipidemia in PNS." (PMID 35399079, 2022). "The present study demonstrated that phlorotannin-rich extracts from A. nodosum and F. vesiculosus may improve the lipid profiles of rats with HED-induced hyperlipidemia by modulating LPL activity, suppressing inflammation, and promoting antioxidant enzyme activity." (PMID 36364926, 2022). "Since the eggplant has induced HMG-CoA reductase activity, eggplant may have shown protective effects on hyperlipidemia via the enhancement rate of degradative processes of cholesterol or induction of lipoprotein lipase activity, and the effective reduction in lipids absorption from the intestine." (PMID 34094022, 2021). "It is observed that when the estradiol 2 level in serum was in a certain amount, osthole (10–20 mg/kg and 10 mg/kg) treated hyperlipidemia and an ovariectomized model could exhibit lower levels of lipoprotein lipase, hepatic lipase, very low-density lipoprotein, chylomicron, and triglyceride." (PMID 32028721, 2020). "Mechanistically, TAC alleviated hepatic lipid accumulation by modulating the activity of key lipometabolic enzymes (HL, LPL, HMGCR), thereby exerting therapeutic effects against hyperlipidemia-combined hepatic steatosis." (PMID 41244823, 2025). "In keeping with intracellular retention of LPL, DKO mice exhibited mild postprandial hyperlipidemia compared to other cohorts." (PMID 37253728, 2023). "In dogs with CS, hyperlipidemia can result from downregulation of LDL receptors and decreased liver uptake of LDL and/or development of insulin resistance, which impairs lipoprotein lipase activity." (PMID 35448493, 2022). "Abnormal LPL will lead to the accumulation of VLDL and CM in the body’s blood, leading to hyperlipidemia." (PMID 34681767, 2021). "This is in agreement with the known role of PCSK6 in lipid metabolism, where it cleaves and inactivates endothelial lipase (EL) and lipoprotein lipase (LPL), which can lead to hyperlipidemia." (PMID 35186008, 2021). "Compared with the NFD group, the expression of the LPL protein and CD36 protein of the hyperlipidemia rats induced by HFD decreased significantly." (PMID 34681767, 2021).
hyperlipidemia (continued). "Meanwhile, some studies on hyperlipidemia showed that GPIHBP1 served as the transporter and the platform for the lipoprotein lipase-mediated lipolysis processing." (PMID 25810903, 2014). "The hyperlipidemia associated with diabetes may result from an accelerated hepatic triglyceride biosynthesis and the release of VLDL without an increase in its rate of clearance from the blood by lipoprotein lipase, which is dependent on the insulin/glucagon ratio." (PMID 23190471, 2012). "Hyperlipidemia can be further exacerbated by low activity of lipoprotein lipase, or by high level of apolipoprotein C-3 (APOC-3), an inhibitor of lipoprotein lipase." (PMID 21773052, 2011). "Eruptive xanthomas are typical of type-I hyperlipoproteinemia (HLP) (congenital lipoprotein lipase deficit) and type-V HLP (familial combined hyperlipidaemia)." (PMID 18474088, 2008). "Consequently, lipoprotein lipase (LPL) and endothelial lipase become more available in the organisms, breaking down triglycerides and other lipids in the bloodstream, which improves hyperlipidemia condition." (PMID 40900281, 2025). "Moreover, in the liver of the hyperlipidemia mice, MDA concentration increased, SOD concentration decreased, and LPL protein expression decreased, indicating that poloxamer 407 inhibited LPL in the liver, consequently triggering lipid peroxidation damage." (PMID 38164484, 2024). "Reduced LPL expression was also negatively correlated with elevated plasma TG levels, suggesting that adipose PAR2 may contribute to the development of hyperlipidemia through downregulation of LPL." (PMID 38973609, 2024). "By administering atorvastatin and varying concentrations of fucoidan sulfate, the levels of HMG-CoA in the liver decreased, while the levels of HL, LPL, and LCAT increased compared to the model group, indicating the pharmaceutical effects of fucoidan on hyperlipidemia in a dose-dependent manner." (PMID 37755081, 2023). "Plasma lipoproteins are hydrolyzed by lipoprotein lipase (LPL); low expression levels or the absence of LPL leads to marked lipemia and triglyceridemia." (PMID 32882776, 2021). "High levels of TG as well as PE may derive from an impairment of lipoprotein lipase (LPL) activity of PbNK65-infected mice, as reported in other models of hyperlipidemia related to infection and inflammation." (PMID 26624290, 2015). "The frequency of the LPL SNPs D9N, N291S and S447X in 100 patients with hyperlipidemia and APOE2/2 genotype has been determined and compared to that in healthy blood donors and patients with hyperlipidemia." (PMID 17727701, 2007). "Patients with nephrotic syndrome often have hyperlipidemia due to the lack of LPL activators." (PMID 36851058, 2023). "In addition, both suppress the production of hepatic ApoB, stimulate the plasmatic depuration of triglycerides via lipoprotein lipase (LPL), raise Very Low-Density Lipoprotein (VLDL-c), reduce the synthesis of LDL-cholesterol and attenuate postprandial lipemia." (PMID 34371804, 2021). "The Zucker fa/fa rat is of great interest as a model of hyperlipidemia in humans, especially for type I and V which are characterized by elevated serum levels of chylomicrons (types I and V) and VLDL (type V), and low (type I) or normal/low (type V) lipoprotein lipase activity." (PMID 30297656, 2018). "In patients with Type V hyperlipidemia, concentrations of both chylomicrons and VLDL are elevated, accompanied with elevated serum levels of cholesterol and both endogenous and exogenous triacylglycerols, with normal or modestly reduced lipoprotein lipase activity." (PMID 30297656, 2018).
diabetes (124 papers, 2002 to 2026). "Beyond its involvement in lipid metabolism, APOC3 is crucial for regulating TG levels and modulating lipoprotein lipase (LPL) activity, both of which are key components in the pathogenesis of diabetes-associated CVDs." (PMID 39684468, 2024). "As already mentioned, type 1 diabetes mellitus is associated with increased LPL activity as well as high placental TG content increasing with the maternal serum HbA1c level." (PMID 38542532, 2024). "In the heart, reduction in LPL, as observed with severe diabetes, causes a switch in substrate utilization to predominantly NEFA." (PMID 39081272, 2024). "Our data demonstrate that Angptl4 expression is up-regulated, and LPL expression and its associated activities are down-regulated, in fibrotic kidneys during diabetes." (PMID 39630889, 2024). "In this sense, some classic CV risk factors, such as age and the presence of diabetes or current smoking, were significantly and positively related to higher serum levels of LPL." (PMID 36982268, 2023). "RC, when degraded and metabolized by lipoprotein lipase, can produce free fatty acids and monoacylglycerols, causing an inflammatory response which in turn leads to diabetes." (PMID 37752554, 2023). "TNF-α-mediated suppression of LPL has been clearly demonstrated in the adipose tissue, and is associated with clinically elevated TGs in patients with diabetes." (PMID 36208911, 2023). "The insulin deficiency probably changes lipid profile in serum due to metabolic complication of diabetes and IR is associated with impaired lipoprotein lipase activity." (PMID 34848753, 2021). "As noted in this study, there has also been a decrease in LPL activity in both animal and human diabetes due to insulin deficiency, because its synthesis is caused by insulin." (PMID 34259114, 2021). "Only three proteins were associated with lower odds of diabetes, i.e. lipoprotein lipase (LPL), IGF-binding protein 2 and paraoxonase 3 (PON-3)." (PMID 31446444, 2019). "In the MR part of our study, however, a positive association between genetically determined LPL concentration and diabetes was found." (PMID 31446444, 2019). "This genetic association study investigates the independent and combined associations of genetically determined differences in lipoprotein lipase–mediated lipolysis and low-density lipoprotein cholesterol metabolism with risk of coronary disease and diabetes." (PMID 30326043, 2018). "Consistently, triglyceride-lowering LPL alleles were strongly associated with lower diabetes risk also in people with genetically lower LDL-C levels." (PMID 30326043, 2018). "Insulin infusions may stimulate LPL activity and lower TG levels in patients with insulin-deficient diabetes presenting with HTG due to insulin deficiency but are ineffective in those with complete LPL deficiency and can cause hypoglycemia." (PMID 41378317, 2025). "In addition, in a large study of genetic variants of the LPL gene associated with lowering of triacylglycerols, a positive association with diabetes was found, giving genetic evidence of a benefit of high LPL activity." (PMID 31446444, 2019). "First, the level of protection from coronary disease and diabetes associated with the ANGPTL4 p.Glu40Lys variant is the same as that of LPL alleles for a given genetic difference in triglyceride levels and is consistent across the population distribution of LDL-C–lowering alleles." (PMID 30326043, 2018). "The ANGPTL4 p.Glu40Lys variant was associated with protection from coronary disease and diabetes, with effect estimates nearly identical to the ones of triglyceride-lowering alleles in LPL for a given genetic difference in triglyceride levels (eFigure 2 in the Supplement)." (PMID 30326043, 2018). "Interestingly, like HNF4A, LPL is also suggested to be a diabetes susceptibility gene by human studies." (PMID 21689475, 2011).
diabetes (continued). "Given elevated THR is associated with a higher risk of developing diabetes, we reasoned from our findings that elevated blood LPL within reference limits could lead to slower increase of THR (i.e., lower ΔTHR) and offers a beneficial effect in disease prevention." (PMID 39557295, 2024). "This systematic review addresses these questions by synthesizing evidence from metabolomic studies to provide a detailed understanding of the interactions between cardiac metabolic changes and LPL activity in Diabetes." (PMID 41373652, 2025). "Outcome (O): Can targeting LPL activity improve cardiac metabolomics and reduce cardiovascular complications in Diabetes?" (PMID 41373652, 2025). "Key studies have highlighted the complex interplay between LPL activity and metabolic pathways in diabetes." (PMID 41373652, 2025). "Understanding how diabetes-induced changes in cardiac metabolism influence LPL activity will be critical in developing new therapeutic strategies to reduce cardiovascular risks." (PMID 41373652, 2025). "Endocrine disorders such as hypothyroidism, hyperadrenocorticism, and diabetes mellitus are known to affect lipid metabolism through decreased activity of lipoprotein lipase (LPL)." (PMID 39858256, 2025). "This occurred in the absence of any change in LPL gene expression suggesting that following diabetes, cardiac LPL activity is mainly modulated by post-translational mechanisms." (PMID 39081272, 2024). "In this review, the mechanisms by which LPL regulates fuel utilization by the heart in control conditions and following diabetes will be discussed in an attempt to identify new targets for therapeutic intervention." (PMID 39081272, 2024). "It is hoped that by understanding LPL regulation and modification following diabetes, we can advance the clinical management of diabetic heart disease as it relates to FA metabolism." (PMID 39081272, 2024). "LPL was significantly down-regulated and the LPL regulators Angptl3 and Angplt4 were significantly up-regulated in diabetes." (PMID 39630889, 2024). "Following diabetes, cardiac GPIHBP1 gene and protein expression also increase with an associated augmentation of coronary LPL activity." (PMID 39081272, 2024). "Regarding tissue-specific detection of LPL following diabetes, adipose tissue and skeletal muscle show low levels of enzyme in homogenates, with virtually no information available on the cardiac content of this enzyme." (PMID 39081272, 2024). "In contrast, we also observed a decline in LPL, both in animals infused with Intralipid and with severe diabetes induced by injecting 100 mg/kg STZ (D100)." (PMID 39081272, 2024). "This transfer is decreased in diabetes, probably as the result of disturbed lipolysis because insulin resistance limits the activity of lipoprotein lipase." (PMID 36979432, 2023). "Management of diabetes with insulin lowers plasma TAG by returning LPL activity to the normal level." (PMID 37970378, 2023). "In genetic studies of various populations, including Asians, the LPL gene was associated with MetS, low HDL-C levels, high blood pressure, diabetes, abdominal obesity, and high TG levels." (PMID 37432202, 2023). "Although plasma concentrations of EL/LPL were elevated in the patients with diabetes, CAD alone had little effect on blood, myocardial and perivascular fat expression of the lipases." (PMID 37686357, 2023). "The strong evidence supporting a causal role for dyslipidemia in diabetes comes from genetic studies of rare mutations in ABCA1, LIPE, LPL, and LRP6, showing that these lipid genes are also linked to hyperglycemia or diabetes." (PMID 35740449, 2022). "The impaired effect of insulin on LPL postprandially is thought to be an important contributor to atherogenic dyslipidemia described in insulin resistance syndrome and type 2 diabetes mellitus." (PMID 34299261, 2021).